CFI (complement factor I)
Diseases named in the same sentence as CFI in open-access papers (continued):
Sharing a sentence is not in itself a finding about the gene and the disease.
Insulin resistance (1 paper, 2019). Increased resistance towards insulin, that is, diminished effectiveness of insulin in reducing blood glucose levels. "protein C receptor, endothelial (EPCR) (PROCR), C1R, CFI, PLAT, C4BPB, and CFB are novel biomarkers for the development of insulin resistance." (PMID 30678306, 2019).
intracranial hemorrhage (1 paper, 2020). Bleeding within the SKULL, including hemorrhages in the brain and the three membranes of MENINGES. "Of note, patients 2 and 3 who harbored CFI mutations died of sepsis and intracranial hemorrhage, respectively." (PMID 33614676, 2020).
lymphoma (1 paper, 2023). A malignant (clonal) proliferation of B- lymphocytes or T- lymphocytes which involves the lymph nodes, bone marrow and/or extranodal sites. "To better understand the role of BAX in CFI sensitivity we generated isogenic BAX wild-type and BAX-deficient clones from two PLK4 sensitive lymphoma lines (OCI-LY19 and Z-138)." (PMID 36934096, 2023). "Together, these data reveal a pattern of efficient cell death induction in CFI and centrinone-sensitive cells, while resistant lymphoma cells showed an accumulation of polyploid cells that failed to undergo apoptosis." (PMID 36934096, 2023). "Together, these results indicate that while CFI and S63845 depend solely on BAX, venetoclax can trigger BAX-independent cell death, most likely through BAK, and enable the elimination of PLK4-inhibited lymphoma cells." (PMID 36934096, 2023). "However, while CFI and venetoclax strongly synergize in lymphoma cells, this combination produces no increase in polyploidy or cell death induction in PBMCs." (PMID 36934096, 2023).
macular dystrophies (1 paper, 2022). "However, genetic testing can identify carriers of variants in complement genes that could be amendable for new (targeted) treatments that are currently in development for AMD (e.g. CFI gene therapy and FH supplementation), and genetic testing can avoid misdiagnosis of inherited macular dystrophies." (PMID 36108770, 2022).
membranoproliferative glomerulonephritis type II (1 paper, 2012). "Dense deposit disease (formerly membranoproliferative glomerulonephritis type II) and C3 glomerulonephritis are also associated with uncontrolled complement activation and mutations in CFH or CFI have been described." (PMID 22834933, 2012).
membranous nephropathy (1 paper, 2022). "Herein we describe a case of aHUS due to a pathogenic mutation in complement factor I that developed after a kidney transplant in a patient with an underlying diagnosis of PLA2R antibody associated-membranous nephropathy." (PMID 35720299, 2022).
non-small cell lung carcinoma (1 paper, 2025). A group of at least three distinct histological types of lung cancer, including non-small cell squamous cell carcinoma, adenocarcinoma, and large cell carcinoma. "The overexpression of CFI is associated with tumor progression and poor prognosis in several cancers, including non-small cell lung cancer, likely via immune evasion and tumor cell proliferation, migration, and invasion." (PMID 41369478, 2025).
ovarian carcinoma (1 paper, 2021). A malignant neoplasm originating from the surface ovarian epithelium. "TTK inhibition by CFI also resulted in slower growth of ovarian cancer cells." (PMID 34876569, 2021).
purpura (1 paper, 2022). A small blood vessel hemorrhage into the skin and/or mucous membranes. "In this study, frozen skin biopsies from the nonlesional skin, initial petechial lesion, and palpable purpura lesion from 10 patients with immunocomplex-mediated small vessel vasculitis were studied immunohistochemically for complement factor I, iC3b, CD11b, and CD14." (PMID 35747245, 2022). "Already, the nonlesional skin revealed marked immunostaining of complement factor I, iC3b, CD11b, and CD14, and their expression increased sequentially in initial petechial and palpable purpura lesions." (PMID 35747245, 2022).
skin cancer (1 paper, 2022). "Most relevant to this work, cultured cSCC respond to both CFH and CFI and the receptor for the more potent C5a can be detected in skin tissue and is expressed in skin cancer lines." (PMID 35223500, 2022).
Stroke (1 paper, 2020). Sudden impairment of blood flow to a part of the brain due to occlusion or rupture of an artery to the brain. "Specifically, elements of the alternative pathway of complement system and MAC proteins, i.e., CFI, C6, C8A, C8G, C9 were found to be activated but also undergoing regulation at 3 months post-stroke." (PMID 32849183, 2020).
virus infection (1 paper, 2022). "Therefore, CFI can be regarded as an important target to control virus infection in human medical research." (PMID 36232671, 2022).
Visual impairment (1 paper, 2020). "Fourth, vision is the most concerned-clinical indicator of AMD, future studies should include the value of the vision and analyze the relationships between CFI polymorphisms and the degree of visual impairment, which may help us better detect disease progression." (PMID 32215612, 2020).
tumor (12 papers, 2019 to 2025). "Complement factor H (CFH) and Complement factor I (CFI) modulated the fundamental processes of the tumor cell, promoting proliferation and tumor progression when tested in animal models." (PMID 39865094, 2025). "Suggestive of a functional role, these regulatory proteins were shown to increase migration and proliferation when added to cSCC cell cultures and CFI appears to be related to tumor growth in vivo." (PMID 35223500, 2022). "Analysis of both TCGA and GTEx datasets indicated significantly higher levels of CFI in 10 tumor types compared to the normal specimens." (PMID 33614625, 2020). "Beyond their known functions, our study suggests that in BLCA, C4A, and CFI may also drive cancer progression by modulating immune-related checkpoints, offering additional insight into their role in tumor immunology." (PMID 40283026, 2025). "While previous studies have noted a role of CFI in GBM, its specific function in tumor-associated vascular hyperplasia remains unclear." (PMID 40867324, 2025). "In addition, CFI expression was positively correlated with the WHO tumor grade, age (≥41 years), and chemotherapy status." (PMID 33614625, 2020). "Moreover, knockdown of CFH and CFI in cSCC tumor cells results in significant inhibition of cell viability and migration in association with potent inhibition of ERK1/2 activation." (PMID 31331124, 2019). "The novel findings regarding candidate genes such as CFI and ELF3 not only enhance our understanding of tumor biology but also pave the way for precision diagnosis and targeted therapy." (PMID 40867324, 2025). "The result showed that the lower mRNA expressions of C3, C5, CFB, and CLU were correlated with more advanced cancer stage, while the lower mRNA expressions of C1S, C8B, CFI, MBL2, and C4BPA were correlated with higher tumor grade in HCC patients." (PMID 34813686, 2022). "Expression of the two main soluble inhibitors of the complement system, CFI and CFH, have been detected in cSCC tumor cells in culture and in vivo and the expression correlates with the progression of cSCC and the expression in normal skin is negative or weak." (PMID 31331124, 2019). "In addition, the mRNA expressions of C1S, C8B, MBL2, CFI, and C4BPA were correlated with tumor grade and prognosis in HCC patients." (PMID 34813686, 2022). "Knockdown of CFI significantly suppressed the growth of cSCC xenograft tumors and promoted inflammation by increasing production of TNF-α and complement activation, as noted by the accumulation of C3b in the tumor edge." (PMID 31331124, 2019). "Given that increased CFH and CFI would decrease C3a and C5a levels, increased CFH would not favor tumor progression through canonical complement pathways." (PMID 35223500, 2022).
infection (11 papers, 2016 to 2025). The state of being infected such as from the introduction of a foreign agent such as serum, vaccine, antigenic substance or organism. "In the 1990s, a study suggested CFI deficiency, resulting from recessive mutations, to be responsible for two cases of recurrent pyogenic infections, including Nm infection." (PMID 32067109, 2020). "CFI deficiency results in uncontrolled continuous activation of the alternative pathway and is associated with recurrent infections from encapsulated bacteria." (PMID 32067109, 2020). "CFI deficiency results in secondary complement C3 deficiency due to uncontrolled spontaneous alternative pathway activation, and CFI-deficient individuals suffer from recurring infections." (PMID 30678719, 2019). "The receiver operating characteristic (ROC) curve showed that protein kinase C-binding protein NELL2, thrombospondin-1, and complement factor I have diagnostic potential for differentiating staphylococci and streptococci intramammary infection and inflammation." (PMID 37889706, 2023). "Furthermore, reports of recurrent infections (including of the respiratory and urinary tract) have also been reported to occur with increased frequency in patients with heterozygotic CFI mutation and partial CFI deficiency." (PMID 29696024, 2018). "Sixteen cattle complement genes, including complement C2, complement factor B (CFB), complement C1r (C1R), C1R-like, C3aR1, complement factor properdin (CFP) and complement factor I (CFI) were upregulated two- to 10.6-fold in response to the infection." (PMID 41398915, 2025). "The evidence reveals that the expression of CFI mRNA is down-regulated in the early stages of pathogen infection or disease onset and displays diverse expression patterns in response to various stimuli in teleost fish." (PMID 36232671, 2022). "During Edwardsiella tarda infection in P. olivaceus, CFI mRNA expressions peak significantly at 6 h post-infection in the spleen and kidney, decreasing at later infection hours." (PMID 36232671, 2022). "The evidence demonstrates that CFI can be a double-edged sword for mammals during pathogen infection, as it is involved in both host immune defense and pathogen evasions." (PMID 36232671, 2022). "At least 11 complement related genes, such as CFI and C7, were significantly impacted by infection in the resistant CHB breed compared to uninfected controls while none of these genes were affected by infection in the susceptible breed." (PMID 27197554, 2016). "This study may provide an essential basis for the full picture of the complex complement regulation mechanism mediated by Df and CFI of the grass carp during pathogen infection." (PMID 36232671, 2022). "In C. semilaevis, CFI mRNA expression was also significantly down-regulated in the liver and intestine post V. anguillarum infection at 6 h, representing an early stage of infection, while sharply up-regulated at the late stage of infection." (PMID 36232671, 2022). "On the other hand, 24 genes were significantly upregulated by infection in the R line of the HSF flock, such as CD19, CD22, CD79B, two complement-related genes CFI and CR2 (complement C3d receptor 2), FGG, and FGA (fibrinogen alpha chain)." (PMID 30678719, 2019). "For example, the expression of CFI, CXCR6, LGALS15, and MMP1 was significantly upregulated while TFF2 mRNA level was significantly repressed by infection only in the resistant breed (CHB), in a good agreement with the RNAseq analysis." (PMID 27197554, 2016). "Several regulators of the complement system, including complement factor H, complement factor I, and CD59, are downregulated by SARS-CoV-2, which may contribute to complement dysregulation during infection." (PMID 39040605, 2024).
infection (continued). "Among them, the expression of 9 genes, such as heat shock protein family A (Hsp70) member 6 (HSPA6), lectin, galactoside-binding, soluble, 15 (LGALS15), and complement factor I (CFI), were significantly enhanced by infection in both R lines when compared to their respective S lines." (PMID 30678719, 2019). "In addition, at least 11 genes implicated in complement activation were significantly impacted by infection in CHB, such as complement factor properdin (CFP, 2.8 fold), complement component 7 (C7, 4.2 fold), and complement factor I (CFI, 12.1 fold)." (PMID 27197554, 2016). "Interestingly, the brother who also was homozygous for the p.His380Arg CFI mutation and had abnormal alternative and classical complement function, and low CFI, CFH, and C3 levels, is currently well, and without any history of recurrent infections." (PMID 29696024, 2018). "Furthermore, a broad activation pattern of the complement system—encompassing both effector components (e.g., C2, C3, C8A, C9) and regulatory proteins (e.g., CFH, CFI, C1QB)—is consistent with prolonged innate immune stimulation in the absence of active infection." (PMID 40869330, 2025).
cancer (10 papers, 2015 to 2025). A tumor composed of atypical neoplastic, often pleomorphic cells that invade other tissues. "Recent studies have correlated CFI expression with cancer prognosis." (PMID 33614625, 2020). "On the other hand, a cancer-specific ubiquitin ligase has been shown to reduce Pcf11 levels specifically but did not alter levels of CPSF, CstF, and CFI complexes or PCF11-interacting proteins." (PMID 36761770, 2023).
bacterial infections (5 papers, 2012 to 2024). "CFI deficiency is possibly an underestimated defect and the eventual existence of this deficiency should be tested in those patients exhibiting low C3 and recurrent bacterial infections." (PMID 22710145, 2012). "As a result, patients with CFI deficiency have a defect in bacterial opsonisation leading to an increase in the susceptibility to recurrent pyogenic infections (Haemophilus influenzae, Neisseria meningitides, and Streptococcus pneumoniae), or non-bacterial infection." (PMID 29696024, 2018). "Herein, we describe a child with recessive mutation in complement factor I (CFI) with deficiency of CFI causing chronic CLV and recurrent bacterial infections." (PMID 29696024, 2018). "In our case, genetic studies found two pathogenic variants in the CFI gene, associated with autosomal recessive CF1 deficiency with a risk of recurrent bacterial infections, often severe pneumococcal disease and autosomal dominant atypical hemolytic uremic syndrome (HUS)." (PMID 39376673, 2024).
genetic disease (3 papers, 2012 to 2022). "CFH was the first protein to be associated with genetic disease, followed by CFI and MCP, and then by C3/C3b." (PMID 25188723, 2014). "In this study, we found that in 45 children diagnosed with aHUS, genetic disorders in complement-regulating genes encoding CFH, CFI, MCP, CFB, C3, and THBD, as well as the presence of αFH with or without a homozygous deletion in CFHR1/3, are linked with clinical presentation, treatment, and outcome." (PMID 22410797, 2012).
immune disorders (2 papers, 2014 to 2019). "Starting from the first reports of complement disease-associated mutations, genetic alterations in four CFH (complement factor H), CFI (complement factor I), MCP (membrane cofactor protein) and complement C3 have increasingly been associated with immune disorders." (PMID 25188723, 2014).
inflammation (2 papers, 2020 to 2025). Aberrant reaction of the microcirculation characterized by movement of fluid and leukocytes from the blood into extravascular tissues. "CFI deficiency can result in uncontrolled activation of the complement pathways in the brain resulting in devastating cerebral inflammation." (PMID 32098865, 2020). "Complete FI deficiency has been associated with a consumptive C3 deficiency and recurrent infections with encapsulated microorganisms or aseptic cerebral inflammation while heterozygous mutations in CFI have been liked to immunopathology in the form of atypical haemolytic uraemic syndrome and AMD." (PMID 39584280, 2025). "These diagnostic challenges may mean that the CFI deficiency is being systematically under-recognized as a cause of fulminant cerebral inflammation." (PMID 32098865, 2020).
infectious disease (1 paper, 2023). A disorder directly resulting from the presence and activity of a microbial, viral, or parasitic agent in humans. "It seems that the clinical expression of the homozygous MCPggaac haplotype depends significantly on additional mutations in the aHUS spectrum, especially CFH and CFI, and if so, various infectious diseases or even drugs trigger aHUS in children who are genetically prone to aHUS onset." (PMID 37685848, 2023).
kidney diseases (1 paper, 2025). "In essence, the authors emphasized the role of the CFI variant p.Ile357Met in complement-mediated kidney diseases." (PMID 40895567, 2025).
retinopathy (1 paper, 2020). "Also, RP1L1, PROM1, CRX, CFI and CFB, and KCNJ13 have been linked to retinopathy." (PMID 33330132, 2020).
CFI also shares sentences with these, for which no sentence is quoted: hemolytic-uremic syndrome (4 papers); membranoproliferative glomerulonephritis (4); C3 glomerulopathy (3); acute hemorrhagic leukoencephalitis (1); amyloidosis (1); antiphospholipid antibody Syndrome (1); asthma (1); autism spectrum disorder (1); Brain atrophy (1); cataract (1); choriocarcinoma (1); colon adenocarcinoma (1); COVID-19 (1); diabetes (1); dry eye (1); edema (1); endometriosis (1); gonococcal infection (1); ischemic stroke (1); lung carcinoma (1); mastitis (1); membranoproliferative glomerulonephritis type I (1); meningitis (1); Methylmalonic aciduria (1); multiple sclerosis (1); neurological diseases (1); neuromyelitis optica (1); Obesity (1); otofaciocervical syndrome (1); pneumococcal meningitis (1).
A further 11 diseases each share a sentence with CFI in 1 paper.